SNRNP40 (small nuclear ribonucleoprotein U5 subunit 40)
Description:
Required for pre-mRNA splicing as component of the activated spliceosome. Component of the U5 small nuclear ribonucleoprotein (snRNP) complex and the U4/U6-U5 tri-snRNP complex, building blocks of the spliceosome. As a component of the minor spliceosome, involved in the splicing of U12-type introns in pre-mRNAs (Probable).
Synonyms: hPRP8BP; PRP8BP; WDR57; SPF38; PRPF8BP; 40K
Tractability: Small molecule: a structure with a bound ligand is known. PROTAC: UniProt records ubiquitination sites on it; ubiquitination databases record sites on it; its protein half-life has been measured.
Gene: Protein-coding gene on chromosome 1 (31,259,568 to 31,296,788, reverse strand). Ensembl gene ENSG00000060688.
Subcellular location: Nucleus
Subcellular location (Human Protein Atlas): Nuclear speckles
Pathways (Reactome):
Metabolism of RNA: mRNA Splicing - Major Pathway; mRNA Splicing - Minor Pathway
Disease: Dengue Virus-Host Interactions
Gene Ontology:
Molecular function: protein binding; RNA binding
Biological process: mRNA splicing, via spliceosome; RNA processing; RNA splicing; RNA splicing, via transesterification reactions; spliceosomal snRNP assembly; spliceosomal tri-snRNP complex assembly; spliceosome conformational change to release U4 (or U4atac) and U1 (or U11)
Cellular component: catalytic step 2 spliceosome; nuclear speck; nucleus; post-mRNA release spliceosomal complex; post-spliceosomal complex; precatalytic spliceosome; spliceosomal complex; U12-type catalytic step 2 spliceosome; U12-type precatalytic spliceosome; U2-type catalytic step 1 spliceosome; U2-type catalytic step 2 spliceosome; U4/U6 x U5 tri-snRNP complex; nucleoplasm; sno(s)RNA-containing ribonucleoprotein complex; U4atac/U6atac x U5 tri-snRNP complex; U5 snRNP
Genetic constraint (gnomAD): Loss-of-function variants: 10 observed, 29.18 expected, observed/expected ratio (o/e) 0.34, 90% interval 0.21 to 0.58. The upper end of that interval is the gene's LOEUF score, 0.58, which puts it in group 2 of 6, group 1 being the genes least tolerant of losing a copy. Missense variants: 270 observed, 333.06 expected, observed/expected ratio (o/e) 0.81, 90% interval 0.73 to 0.9. Synonymous variants: 117 observed, 131.26 expected, observed/expected ratio (o/e) 0.89, 90% interval 0.77 to 1.04.
Homologues: Orthologues: chimpanzee SNRNP40 (100% identical), pig SNRNP40 (99% identical), rabbit SNRNP40 (99% identical), dog SNRNP40 (99% identical), rat Snrnp40 (99% identical), mouse Snrnp40 (98% identical), guinea pig SNRNP40 (98% identical), macaque SNRNP40 (97% identical), tropical clawed frog snrnp40 (86% identical), zebrafish snrnp40 (82% identical), Drosophila melanogaster CG3436 (56% identical), Caenorhabditis elegans snrp-40.1 (50% identical), and 1 more. Paralogues in human: WDR5B (25% identical), POC1B (24% identical), AHI1 (24% identical), WDR5 (23% identical), TEP1 (22% identical), WDR7 (22% identical), MAPKBP1 (22% identical), WDR17 (22% identical), POC1A (21% identical), WDR27 (21% identical), WDR62 (21% identical), WDR75 (19% identical), and 14 more.
Diseases named in the same sentence as SNRNP40 in open-access papers:
SNRNP40 is named in the same sentence as 9 diseases in open-access papers, as found by Europe PMC text mining. Sharing a sentence is not in itself a finding about the gene and the disease. The quoted sentences say what the papers report.
breast carcinoma (1 paper, 2016). "Consistent with these functional findings, decreased SNRNP40 transcript-level expression in bulk primary breast cancer samples was associated with increased metastatic relapse outcomes in multiple independent data sets." (PMID 27138336, 2016). "Indeed, engineered variation of the SNRNP40 spliceosomal gene's expression among cells within a breast cancer population promoted their metastatic fitness." (PMID 27138336, 2016).
COVID-19 (1 paper, 2022). A disease caused by infection with severe acute respiratory syndrome coronavirus 2. "Our results showed that six spliceosomal component proteins (DDX5, DDX17, DDX39B, PRPF6, SNRNP40, and SNRNP200) were significantly down-regulated in COVID-19 patients." (PMID 35421082, 2022). "Specifically, two small nuclear ribonucleoprotein U5 subunits (SNRNP40 and SNRNP200) and multiple splicing factors (e.g., HNRNP A0, A2B1, A3, DL, F, H1, H2, L, LL, R, U, UL1, UL2 and SRSF6) were significantly under-expressed in the COVID-19 patients." (PMID 35421082, 2022).
cancer (4 papers, 2016 to 2021). A tumor composed of atypical neoplastic, often pleomorphic cells that invade other tissues. "Furthermore, recurrent somatic mutations or changes in the expression levels of a number of U5 snRNP proteins (PRPF6, PRPF8, EFTUD2, DDX23, and SNRNP40) have been associated with human cancers." (PMID 33584830, 2021). "However, somatic mutations in PRPF8 have now been linked to myeloid neoplasms, while altered expression levels of several other U5 snRNP proteins (PRPF6, EFTUD2, SNRNP40, and DDX23) have been associated with human cancer." (PMID 33584830, 2021). "While tumours can achieve reduced SNRNP40 expression through mean expression alteration, we show in our experimental model that cancer subpopulations may achieve SNRNP40 silencing through deregulation in a subset of cells that may not be apparent from averaged measurements derived from bulk tumours." (PMID 27138336, 2016). "For example, the methylation regions located in ACAA2, NUSAP1, OGFOD1, PSMD5, SNRNP40, USP37 and XRCC6 are shared by five cancers (i.e., BRCA, CESC, COAD, KIRP and SARC)." (PMID 34464378, 2021). "However, the underlying mechanisms of precisely how variable expression of splicing factors, including SNRNP40, promote metastatic progression and the overall contribution to cancer progression is not understood." (PMID 33584830, 2021).
infection (2 papers, 2016 to 2025). The state of being infected such as from the introduction of a foreign agent such as serum, vaccine, antigenic substance or organism. "In contrast, no significant changes were observed for CD2BP2, DDX23, EFTUD2, SNRNP40 (U5 snRNP components) or SF3A2 (U2 snRNP component) levels up to 48 hours of infection as compared with those in uninfected cells." (PMID 27575636, 2016). "Specifically, SNRNP40 and SNRNP70 retained the appearance of nuclear speckles following infection, while WDR12 retained a diffuse nuclear distribution." (PMID 40577456, 2025).
SNRNP40 also shares sentences with these, for which no sentence is quoted: chronic pancreatitis (1 paper); neurodevelopmental disorder (1); primary immunodeficiency (1); tumours (1); viral myocarditis (1).